ALDH1A1 (aldehyde dehydrogenase 1 family member A1)
Diseases named in the same sentence as ALDH1A1 in open-access papers (continued):
Sharing a sentence is not in itself a finding about the gene and the disease.
cancer (continued). "As one of the intrinsic properties of cancer stem cells is drug resistance, in this study, we examined the correlation between the level and activity of endogenous ALDH1A1 and GEM resistance in the MIA PaCa-2 cell line that contains high expression levels and activity of ALDH1A1." (PMID 22710732, 2012). "Furthermore, recent studies demonstrated a cancer-prone stem cell niche at the hilum of the OSE in mice, characterized by cells expressing numerous stemness markers (ALDH1, LGR5, LEF1, CD133, CK6B); five stem cell markers (NANOG, SFRP1, LHX9, ALDH1A1, and ALDH1A2) were detected in both OSE and FTE." (PMID 31277278, 2019). "In this study, we evaluated the expression level of ALDH1A1 in primary HCC surgical sections with two methods, IHC staining and qRT-PCR, investigated the relationship between ALDH1A1 and clinicopathological findings, and examined whether ALDH1A1 deserves to be a cancer stem cell marker in HCC." (PMID 26160842, 2015). "There are currently no specific ALDH1A1 and PLK3 inhibitors available for clinical cancer treatment." (PMID 38169509, 2024). "Here, we demonstrated that the ovarian CSC subpopulation can be maintained via cancer cell dedifferentiation, and DDB2 is able to suppress this non-CSC-to-CSC conversion by repression of ALDH1A1 transcription." (PMID 29752431, 2018). "In cancer therapy, ALDH1A1 provides a useful therapeutic CSC target in tissue types that normally do not express high levels of ALDH1A1, including breast, lung, esophagus, colon and stomach." (PMID 26783961, 2016). "In double-staining IHC, ALDH1A1 was not co-expressed with BMI1, EpCAM, CD13, CD24, CD90 and CD133, which reported as cancer stem cell markers in HCC." (PMID 26160842, 2015). "However, for the stemness marker correlation analysis, NOTCH3 did not exhibit co-expression with ALDH1A1 together with other stemness markers, suggesting NOTCH3 has little impact on keeping the cancer stemness in gastric tumorigenesis." (PMID 33452458, 2021). "Cell morphology and p-MLC2 levels were assessed as amoeboid markers; ki-67 staining as a proliferative marker; WNT11, WNT5B and DAAM1 expression as non-canonical Wnt markers; and ALDH1A1, ALDH1A3, CD44, NANOG and OCT4 were evaluated as cancer stem cell-related markers." (PMID 33082334, 2020). "Several of these isoforms have been reported by other groups to be involved in ALDEFLUOR assay, namely ALDH1A1, ALDH1A2, ALDH1A3, and ALDH2, while the other five ones have seldom been described and their role in cancer have not yet been explored in detail." (PMID 30220009, 2019). "Interestingly, ALDH1A1 was not co-expressed with EpCAM, BMI1, CD13, CD24, CD90 and CD133 which have been reported to be cancer stem cell markers in HCC." (PMID 26160842, 2015). "Given that DDB2 silencing promotes the cancer cell dedifferentiation, and ALDH1A1 plays a critical role in DDB2 silencing-induced expansion of the CSC subpopulation, we sought to determine whether ALDH1A1 is essential for DDB2 silencing-augmented non-CSC-to-CSC conversions." (PMID 29752431, 2018).
tumor (877 papers, 2007 to 2026). "Tumor-associated stromal cells exhibited ALDH1A1 expression ranging from 0.00 to 99.45%, with a median of 70.45%." (PMID 39744576, 2025). "In the male subgroup, the median ALDH1A1 expression in tumor cells was 81.51%, with a range from 0.00 to 99.75%, and 63.34% in tumor-associated stromal cells, with a range from 0.00 to 96.84%." (PMID 39744576, 2025). "ALDH1A1 upregulation was associated with increased tumour aggressiveness, treatment resistance, and poor prognosis in many tumours." (PMID 40433700, 2025). "In the female subpopulation, low ALDH1A1 in either tumor or stroma correlated with an increased risk of death (tumor: HR = 2.8; CI [1.27, 6.17]; p = 0.01; stroma: HR = 2.36; CI [1.0, 5.55]; p = 0.049)." (PMID 39744576, 2025). "Subpopulation analysis indicated that several tumor cell subtypes were markedly linked to resistance, with elevated expression levels of ALDH1A1 and S100A4 in the resistant subpopulation, notably correlating with various immunological and metabolic pathways." (PMID 40093000, 2025). "As in the univariable analysis low ALDH1A1 expression correlated with an increased risk of death (tumor: HR = 1.95; CI [1.04, 3.66]; p = 0.036; stroma: HR = 2.23; CI [1.11, 4.51]; p = 0.025)." (PMID 39744576, 2025). "To unveil the downstream signaling pathways implicated in ALDH1A1-mediated tumor immune escape, we performed RNA-sequencing and differential analysis in shALDH1A1 HT29 cells and CTRL cells." (PMID 39107297, 2024). "In prostate adenocarcinoma, ALDH1A1 shows a statistically significant association with tumor stage (p < 0.001), extraprostatic extension (p < 0.001), and lymphovascular invasion (p = 0.001)." (PMID 37298333, 2023). "In non-small cell lung cancer, which is the most common type of neoplasia worldwide, ALDH1A1 is highly expressed after the loss of the aryl hydrocarbon receptor block on carcinogenesis by constitutively active KRAS." (PMID 37298333, 2023). "This study further confirmed the increased oncogenicity of the CD44+/CD24-/ALDH1A1+ combination phenotype and its association with the increased tumor grade and clinical prognostic stage." (PMID 35814382, 2022). "There is limited data regarding the association between ALDH1A1 expression and TILs in different neoplasms." (PMID 36139578, 2022). "Our data demonstrated that high co-expression of SALL4/ALDH1A1 was found to be significantly associated with tumor aggressiveness and worse DSS or PFS in SOC patients." (PMID 35090523, 2022). "A H3K36me3 methylation mark of the ALDH1A1 promoter was found in response to irradiation with 4Gy of X-rays and was associated with an increase in ALDH1A1 transcription, indicating tumor cell reprogramming." (PMID 34572930, 2021). "The results show that among the 6 CSC markers investigated, the expression of CD44 and its variant isoforms (CD44v6 and CD44v8-10), and also ALDH1A1, were associated with tumor progression and poor outcome of CCA patients, including short RFS and OS." (PMID 32039729, 2020). "ALDH1A1 is overexpressed in several malignancies and TICs, which are associated with chemoresistance, poor prognosis, and tumor aggressiveness." (PMID 32575908, 2020). "ALDH1A1 expression is associated with features of poor prognosis, including a poorly differentiated histology and ‘right-sidedness’ of the primary tumor, and with shorter overall survival." (PMID 30308036, 2018). "This revealed that treatment prior to tumor resection was associated with significantly higher levels of ALDH1A1, both in primary tumors and metastases." (PMID 30308036, 2018). "Our results show that high ALDH1A1 levels are linked to a shorter OS and to tumor characteristics that are associated with a shorter survival in CRC." (PMID 30308036, 2018). "In one study, ALDH1A1 expression was found to be associated with favourable prognosis, whereas in other studies enhance levels of ALDH1A1 was associated with severe tumor phenotypes and poor prognosis." (PMID 28415606, 2017).
tumor (continued). "Association between ALDH1A1/B1/L1 mRNA expression and the tumor biological features in HBV-related HCC patients." (PMID 28792511, 2017). "The ALDH1A1-high group was significantly associated with low serum levels of α-fetoprotein, small tumor diameter, very little lymphovascular invasion, more differentiated pathology and good stage." (PMID 26160842, 2015). "Recently, ALDH1A1 was confirmed to be involved in many pathways regulating biological processes associated with tumor cells." (PMID 24671051, 2014). "We next sought to evaluate the correlation between tumor hypoxia and stem cell markers, since hypoxia has been reported to be associated with the induction of ALDH1A1 and CD133 in some experimental models." (PMID 24500694, 2014). "The overall analysis showed significant association between ALDH1A1 expression and tumor size, histological grade, LNM, and the expression of ER, PR, and HER2." (PMID 24938375, 2014). "ALDH1A1 expression has been linked to more aggressive tumours suggesting a possible role in the invasive/drug resistance pathways." (PMID 19216797, 2009). "Ex vivo drug testing revealed a striking response: the mTOR inhibitor Sapanisertib induced extensive tumor necrosis and was associated with near-complete depletion of ALDH1A1+ and NTN4+ states, accompanied by strong stress/apoptosis signatures and reduced endothelial cells." (PMID 42070010, 2026). "Notably, tumor positivity for c-MYC and ALDH1A1 was associated with longer disease-specific survival, thus suggesting their role as tumor suppressors." (PMID 41463190, 2025). "However, Suzuki et al174found that strong ALDH1A1 expression was associated with better tumor differentiation and had little correlation with stem cell characteristics in HCC cells." (PMID 40157374, 2025). "Elevated levels of ALDH1A1 have been linked to tumor development by influencing the immune system." (PMID 40119647, 2025). "Additionally, these observations need to be validated in in vivo models to better understand the impact of ALDH1A1 loss within the tumor microenvironment and its potential therapeutic implications." (PMID 40076923, 2025). "Through further analysis of xenograft tumor models in immune-normal mice and flow cytometry, we found that deficiency in ALDH1A1 could promote immune system suppression of tumors in vivo." (PMID 39107297, 2024). "ALDH1A1 is associated with the tumour microenvironment by promoting angiogenesis." (PMID 37007016, 2023). "Moreover, we found that the co-expression of SALL4/ALDH1A1 proteins is associated with more aggressive tumor behavior, more advanced disease, and poor DSS, or PFS in SOC cases." (PMID 35090523, 2022). "Although, ALDH1A1 expression was associated with tumor size (p = 0.042)." (PMID 34778599, 2021). "Although many studies have reported that the expression of CD44, CD44v, CD133, EpCAM and ALDH1A1 is associated with tumor progression and can be used to predict patient’s outcome, their prognostic significance in the recurrence of CCA in patients has not been elucidated." (PMID 32039729, 2020). "ALDH1A1 has been associated with CSC populations in many tumor types." (PMID 32015486, 2020). "To test this hypothesis, we analyzed whether gene expression of ALDH1A1 is positively associated with gene expression of NR1I2 in two independent CRC cohorts containing primary tumor samples versus two cohorts containing metastatic tissue." (PMID 30308036, 2018). "In the MCF-7 ALDH1A1KD tumors, Ki67 staining was detected in 10–30% of tumor cells (+), whereas it was 70% in ALDH1A1+ or Scr tumors (+++) indicating that high proliferative activity was associated with ALDH1A1 expression in tumors." (PMID 30541574, 2018). "Moreover, because autophagy has been shown to be involved in modulating tumor cell motility and invasion, we checked the effect of ALDH1A1 knockdown on AuO‐induced autophagy activity." (PMID 28722353, 2017).
tumor (continued). "At later stages in human tumors, systemic therapy can cause the selection of tumor cells with high nuclear DKK-1 that by inducing genes such as ALDH1A1 and REPS2 may be responsible for chemoresistance." (PMID 25788273, 2015). "In addition, one study reported that high levels of ALDH1A1 in tumor stromal tissues are associated with better clinical outcomes." (PMID 26462023, 2015). "This may be associated with differentiation status, as strong ALDH1A1 expression was exclusive to well differentiated tumours." (PMID 19216797, 2009). "Additionally, xenograft tumors derived from trastuzumab-sensitive BT474 cells pretreated in vitro with DSF/Cu exhibited a significant decrease of tumor growth associated with the downregulation of p95HER2 and ALDH1A1 protein content compared to untreated tumors." (PMID 34638263, 2021). "The cutoffs for tumor- and stromal-cell expression of ALDH1A1 were set at 94.92% and 88.45%, respectively." (PMID 39744576, 2025). "CD44, CD133, and ALDH1A1 are widely used as stem cell markers and play critical roles in promoting tumor growth, invasion, and recurrence." (PMID 40240323, 2025). "ALDH1A1 expression in both tumor and stromal cells was assessed for all patients, revealing a skewed distribution." (PMID 39744576, 2025). "In the female population, the median ALDH1A1 expression in tumor cells was 92.56%, with values ranging from 2.03 to 99.66%." (PMID 39744576, 2025). "Previous reports on ALDH1A1, as a marker of cell stemness, have been verified in various solid tumors to promote self-renewal, drug resistance, and tumor development, which is consistent with the conclusions of this study." (PMID 40886002, 2025). "This split showed significantly prolonged overall survival in the female subpopulation for high ALDH1A1 expression in tumor (p = 0.0077) and stromal cells (p = 0.043)." (PMID 39744576, 2025). "This indicated that the expression of ALDH1A1 is crucial for IL-8 to promote ICC progression, and inhibiting IL-8/CXCR2 can also inhibit the tumor-promoting effect of ALDH1A1." (PMID 40008905, 2025). "Tumor positivity to c-MYC and ALDH1A1 was associated with longer disease-specific survival, suggesting their potential role in ITAC prediction." (PMID 41463190, 2025). "Univariate Cox regression model showed prognostic significance for ALDH1A1 expression in both tumor and stromal cells." (PMID 39744576, 2025). "This distribution pattern of ALDH1A1-expressing cells was also detected in 30% of OD cases, and in the para-tumor epithelium of 56.6% of the OSCC samples that included such areas (n = 62)." (PMID 41228340, 2025). "The effects of IL-8 and ALDH1A1 on tumor growth and NF-κB expression were validated using subcutaneous tumors in nude mice." (PMID 40008905, 2025). "ALDH1A1+1A3 dual peptides-DC vaccine mediated an additive anti-tumor effect compared to single peptide-DC vaccines in a D5 melanoma model." (PMID 39990669, 2025). "ALDH1A1 can also promote tumor angiogenesis in melanoma by activating the IL-8/Notch signaling pathway." (PMID 40008905, 2025). "Tumor positivity to ALDH1A1 was found in 9 of 17 cases (52%), and its expression (cytoplasmatic or nuclear) was significantly associated with a favorable OS (p = 0.05) and DFS (p = 0.021)." (PMID 41463190, 2025). "ALDH1A1 overexpression in both tumor and stromal cells has been shown to favorably impact overall survival in iCC." (PMID 39744576, 2025). "Cox regression analysis indicated significant hazard ratios for ALDH1A1 expression in both tumor and stromal cells, in univariable as well as multivariable models." (PMID 39744576, 2025). "The Pearson ́s Chi-squared test showed a significant correlation of ALDH1A1 Expression within tumor and its surrounding stroma cells (p = < 0.001)." (PMID 39744576, 2025). "The tumour stemness marker ALDH1A1 plays a vital role in tumour initiation, progression and recurrence." (PMID 40665579, 2025).
tumor (continued). "This study further elucidated the tumor biological behavior of ALDH1A1 overexpression, including the positive feedback loop of IL-8 autocrine activation involving NF-κB." (PMID 40008905, 2025). "In OSCC, the frequency of ALDH1A1+ cells was found to be even more heterogeneous than in OD, with tumor islands showing more than 50% ALDH1A1+ cells being detected next to islands scoring 0%." (PMID 41228340, 2025). "As a result, the multi-CSC peptides-nanodisc vaccine reduced tumor growth and extended animal survival significantly more than ALDH1A1/1A3 peptides-ND." (PMID 39990669, 2025). "For example, a study analyzed the expression of seven markers (ALDH1A1, ABCG2, various variants of CD44, CD133, CD271, and Nestin) in 40 cell cultures of primary strains and 40 tumor fragments, making a comparison with normal melanocytes and fibroblasts." (PMID 40806546, 2025). "Nevertheless, more and more publications indicate a protective biological function of ALDH1A1 within the tumor, as well as within the surrounding tumor stroma 23-28." (PMID 39744576, 2025). "ALDH1A1 overexpression, both in tumor and stromal cells, correlates with favorable overall survival in iCC." (PMID 39744576, 2025). "In comparison to the normal group, the expression levels of ACADM and ALDH1A1 were significantly down‐regulated in the tumor group, whereas the expression level of DHCR7 was significantly up‐regulated in the tumor group." (PMID 39716927, 2025). "High expression of ALDH1A1 was detected in OD patient material and derived cell lines, as well as in the pre-tumor epithelium of OSCC patients." (PMID 41228340, 2025). "Low ALDH1A1 expression correlated with a dismal survival (tumor: HR = 2.19; CI [1.22, 3.93]; p = 0.008; stroma: HR = 2.4; CI [1.23, 4.67]; p = 0.01)." (PMID 39744576, 2025). "Studies are underway to profile these clones and to expand functional knockout studies to include other TNBC cell lines and patient-derived samples to understand ALDH1A1 function across different tumor microenvironments and genetic backgrounds." (PMID 40076923, 2025). "In both tumor and stromal cells, high ALDH1A1 expression correlated with significantly longer patient overall survival (ALDH1A1 expression in tumor p = 0.0068; ALDH1A1 expression in stroma p = 0.008))." (PMID 39744576, 2025). "ALDH1A1 promotes tumor progression by enhancing the transcriptional activity of both the androgen receptor (AR) and the retinoic acid receptor (RAR), whereas ALDH1A3 appears to exert inhibitory effects." (PMID 40708788, 2025). "The treatment responsiveness of all patients was summarized, revealing a significant positive correlation between the relative increase in tumor diameter and ALDH1A1 expression level." (PMID 39107297, 2024). "These preclinical results provide further validation of the potential benefits of targeting the ALDH1A1-ZBTB7B axis in tumor patients with high expression of ALDH1A1 and ZBTB7B." (PMID 39107297, 2024). "As observed for its mRNA, the tumor aggressiveness marker ALDH1A1 increased more than 4-fold in the MS analysis." (PMID 38388710, 2024). "Conversely, patient 13, with relatively high ALDH1A1 expression, showed tumor growth after treatment." (PMID 39107297, 2024). "Tumor growth was inhibited by cpd-22, and active-p-ILKSer246 and ALDH1A1 levels in the tumors were decreased by treatment with cpd-22." (PMID 38822429, 2024). "Previous study has indicated that ALDH1A1 plays a role in lowering intracellular pH, supporting the maintenance of an acidic tumor microenvironment." (PMID 39107297, 2024). "The overexpression of ALDH1A1 is reported in 56.8% of clear cell RCC (ccRCC) samples, and high ALDH1A1 expression is associated with tumor stage, invasion, and recurrence risk." (PMID 39796106, 2024).